RNU6-211P (RNA, U6 small nuclear 211, pseudogene)
Gene: Small nuclear RNA gene on chromosome 5 (80,365,726 to 80,365,832, reverse strand). Ensembl gene ENSG00000206774.
Homologues: Orthologues: chimpanzee U6 (93% identical), macaque U6 (93% identical), guinea pig U6 (85% identical), guinea pig U6 (78% identical), rat LOC120093925 (72% identical), mouse Gm55609 (68% identical). Paralogues in human: RNU6-1152P (96% identical), RNU6-310P (93% identical), RNU6-116P (93% identical), RNU6-15P (93% identical), RNU6-196P (93% identical), RNU6-20P (93% identical), RNU6-35P (93% identical), RNU6-434P (93% identical), RNU6-812P (93% identical), RNU6-1145P (92% identical), RNU6-1316P (92% identical), RNU6-16P (92% identical), and 1287 more.